IL1B (interleukin 1 beta)
Diseases named in the same sentence as IL1B in open-access papers (continued):
Sharing a sentence is not in itself a finding about the gene and the disease.
epilepsy (continued). "Hidradenitis suppurativa (HS) is the main pathology of cognitive and functional disorders mainly related to epilepsy, primarily temporal epilepsy, with the release of IL-1b, TNF, and IL-6." (PMID 39166055, 2024). "Combining the results of both algorithms, we identified five feature genes (CD38, FAIM2, IL1B, PAWR, S100A8) as diagnostic biomarkers for epilepsy grouping." (PMID 38384278, 2024). "Novel therapeutic targets of epilepsy include interleukin (IL)-1β, cyclooxygenase (COX), tumor necrosis factor (TNF), and IL-6 receptor." (PMID 39723425, 2024). "In the study, IL‐1β, TNF‐α, and Iba‐1 levels were found to be high in KA‐induced epilepsy, whereas overexpression of circHivep2 dramatically decreased the elevated levels of IL‐1β and TNF‐α." (PMID 38676299, 2024). "Five feature genes, namely CD38, FAIM2, IL1B, PAWR, and S100A8, were identified as diagnostic biomarkers for epilepsy subtyping, forming the basis for constructing a disease classification model." (PMID 38384278, 2024). "As for epilepsy development, chronic upregulation of IL-1β can influence both excitatory and inhibitory neurotransmission, resulting in hyperexcitability and decreased seizure threshold." (PMID 39014496, 2024). "To ascertain the involvement of neuroinflammation in the therapeutic mechanism of Gent-treated epilepsy seizures in mice, we conducted an evaluation of the protein levels of IL-1β, TNF-α, and IL-6 in hippocampi using Western blot analysis." (PMID 39598325, 2024). "At 72 h following KA‐induced epilepsy, circHivep2+ exosomes further reduced the levels of pro‐inflammatory cytokines, IL‐1β, cytokine release, and TNF‐α in the hippocampus." (PMID 38676299, 2024). "As a result, our further screening demonstrated that pro-inflammatory cytokines (PICs), such as IL-1β, IL-6, and TNF-α, and the TLR4/NF-κB pathway were associated with APS' effects in treating epilepsy." (PMID 38405667, 2024). "IL-1β, a potent pro-convulsant, demonstrated elevated expression in epilepsy patients, indicating its potential as a therapeutic target." (PMID 38384278, 2024). "Several studies have used anakinra (an antagonist of the IL-1R1 receptor) or anti-IL-1β monoclonal antibodies in animal models, both of which have been shown to reduce the occurrence of epilepsy." (PMID 38074156, 2023). "In rat models of kainic acid-induced epilepsy, down-regulation of miR-34c-5p, up-regulation of HMGB1 and IL-1β, and increased hippocampal neuron loss occur in drug-resistant animals." (PMID 37653173, 2023). "For instance, interleukin‐1β (IL‐1β) and its receptor IL‐1R1 have been reported both in human epilepsy foci and in experimental models of seizures and epilepsy." (PMID 36440924, 2023). "In this study, we found that levels of TNF-α and IL-1β were significantly higher than those in the control group, indicating that TNF-α and IL-1β played a vital role in the pathogenesis of epilepsy." (PMID 38077432, 2023). "Of note, several P2X7R-dependent inflammation markers have been shown to be dysregulated in the blood of epilepsy patients (e.g., IL-1β, IL-18), potentially serving as useful surrogate makers of P2X7R activation/inhibition." (PMID 36982485, 2023). "Interleukin-1β (IL-1β), its receptor (IL-1R), and the receptor antagonist are all known to be altered in the brain of various animal models of epilepsy." (PMID 36672083, 2023). "Researchers have also provided a vast amount of evidence supporting the involvement of IL-1β in epilepsy." (PMID 38077432, 2023). "Meanwhile, exogenous IL-1β can increase the proportion of epilepsy in rats after prolonged febrile convulsion." (PMID 38074156, 2023). "The elevated expression of miR-146a and IL-1β in astrocytes of epilepsy models indicates their involvement in modulating the IL-1β-induced inflammatory response." (PMID 37653173, 2023). "The CSF–serum IL-1β ratio was shown to be elevated in TBI patients who are prone to developing epilepsy." (PMID 36767668, 2023).
epilepsy (continued). "Here, HMGB1/TLR4 and IL-1β/IL-1R inflammasomes in the pathogenesis of epilepsy are reviewed and future perspectives are outlined." (PMID 35837232, 2022). "IL-1β levels are significantly increased in the brain tissue and plasma samples from animal models of epilepsy and patients with temporal lobe epilepsy." (PMID 35837232, 2022). "Noteworthy, the blockade of Kv1.3 attenuated KA-induced epilepsy and inhibited microglial activation and the release of proinflammatory cytokines (such as IL-1β, IL-6, and TNF-α) through the Ca2+/NF-κB signaling pathway." (PMID 36499018, 2022). "Several studies on epilepsy revealed that IL-1β is related to the pathomechanism of epilepsy-related depression." (PMID 35504954, 2022). "During epilepsy, inflammatory activation of glial cells leads to the production of interleukin-1-beta, interleukin-6, and TNF-α, which are able to perpetuate inflammation to other neurons and recruit adaptive immune response cells in the brain." (PMID 36138769, 2022). "A comprehensive study on the role of IL-1β in epilepsy (2007) showed that IL-1β signaling induces neuronal excitability through alterations of ion channels and neurotransmitter receptors, and stimulates an inflammatory cascade through NF-κB." (PMID 35656438, 2022). "The most convincing evidence supporting the involvement of cytokines in epileptogenesis and epilepsy progression originated from studies on IL-1β, its corresponding receptor (IL-1R1) and its antagonist (IL-1RA)." (PMID 35625063, 2022). "In KA-induced rodent epilepsy models, intrahippocampal injection of IL-1β worsened and prolonged both electrographic and behavioral seizure activity." (PMID 35326336, 2022). "In various animal models of epilepsy, the pharmacological blockade of IL-1β through IL-1RA reduced seizures and signs of cellular injury, suggesting that the treatment of peripheral autoinflammation can be beneficial for intractable epilepsy." (PMID 35326336, 2022). "IL-1B is known to be an important inflammatory marker and is found to induce epilepsy by inducing inflammation in the brain." (PMID 36438833, 2022). "Studies have shown that the genes for IL-1β, IL-1R1, and IL-1RA are overexpressed in rodent models of epilepsy." (PMID 35720723, 2022). "A comparison of IL-1β levels in the blood and microdialysates of the epilepsy group demonstrated partly-opposed time courses." (PMID 35625063, 2022). "IL-1β is the only cytokine also upregulated in the lateral temporal neocortex, highlighting its central role in epilepsy." (PMID 36172274, 2022). "In vitro studies and animal models showed that an increase in IL-1β contributes to initiating seizures and epilepsy." (PMID 35656438, 2022). "CSF samples of children with epilepsy showed significantly elevated IL-1β values compared to controls." (PMID 35625063, 2022). "The prototypical pro-inflammatory interleukin-1β (IL-1β) has a prominent role in these inflammatory processes in both epileptic patients and animal models of epilepsy." (PMID 35741692, 2022). "VX-765 reduces disease severity and the expression of IL-1β and IL-18 in animal models of RA, skin inflammation, and epilepsy." (PMID 35628185, 2022). "Previous findings provide strong support for the involvement of pro-inflammatory cytokines in the pathophysiology of epilepsy with elevated levels of the pro-inflammatory cytokines IL-1β, IL-6, IL-10, IL-17, IFN-α, and TNF-α." (PMID 34791253, 2022). "Several lines of evidence have shown that IL-1β exacerbates seizure activity in experimental models of epilepsy, leading to the assumption that there is an involvement of IL-1 signaling in the pathophysiology of epilepsy." (PMID 35163653, 2022). "Hyperexpression of CCL2 in epilepsy is suggested to increase seizure-induced IL-1β production and neuronal cell death." (PMID 35898503, 2022).
epilepsy (continued). "HMGB1, IL-1β, and S-100B can be molecular markers in the incidence of epilepsy characterized by changes in serum concentrations so that they have clinical significance in the epileptic process and can predict outcomes." (PMID 36310854, 2022). "In this study, maximal IL-1β-release occurred on day 8 and converged to the baseline after established epilepsy." (PMID 35625063, 2022). "Based on our results, HsTx2 suppresses the progression of PTZ-induced epilepsy in a mouse model and alleviates IL-1β-induced astrocyte inflammation." (PMID 36457055, 2022). "Recent studies, including our own, have demonstrated the correlation between IL-1β and IL-1R1 levels and the severity of epilepsy." (PMID 34208064, 2021). "Cerebrovascular pericytes undergo redistribution and remodeling, potentially contributing to BBB permeability, and inflammatory cytokines including IL-1β, TNFα, and IL-6 are deeply involved in the pathogenesis of pericyte-mediated epilepsy." (PMID 33922369, 2021). "Preclinical data indicate increased hippocampal synthesis of IL-1β mRNA and protein in a number of experimental animal models of seizures and epilepsy induced by electrical or chemical triggers." (PMID 33377994, 2021). "An in vitro study suggested that after epilepsy, IL-1β mRNA, IL-6 mRNA, and TNF-α mRNA were expressed by microglia and astrocyte." (PMID 34976232, 2021). "A related study demonstrated that GRIN2B, BDNF, and IL-1β gene significantly were upregulated and GRIN2B was positively correlated with the expressions of BDNF and IL-1β gene in people with epilepsy." (PMID 35069111, 2021). "IL-1β has been identified to be one of the most implicitly involved cytokines in the pathogenesis of epilepsy; IL-1β directly excites neurons via N-methyl-d-aspartate receptor activation." (PMID 33922369, 2021). "In epilepsy, the activation of NF-κB in microglia has been known to cause neuroinflammation by inducing pro-inflammatory cytokines and chemokines (TNF-α, IL-1β, MIP-1α, and MCP-1)." (PMID 34680566, 2021). "The most prominent one is IL-1β, which is produced in the brain of human patients with pharmaco-resistant epilepsy and was also shown to lower the seizure threshold in animals." (PMID 34966269, 2021). "Carriers of at least one polymorphic IL1B rs16944 allele were more likely to develop epilepsy only when carrying at least one polymorphic CARD8 rs2043211, further emphasizing the important role of CARD8-IL1B gene–gene interaction." (PMID 34573127, 2021). "The increase in acetylcholinesterases was related to an increase in inflammatory cytokines (IL-1β, IL-12, and TNFα), activation of microglia, and development of epilepsy." (PMID 34948222, 2021). "Multiple studies have found that various biological samples such as serum and cerebrospinal fluid of patients with epilepsy are accompanied by the increase of IL-1β." (PMID 33959658, 2021). "Since this study focused on the role of HIF-1α in VPA-resistant epilepsy, we prioritized IL-1β and TNF-α that directly interact with HIF-1α." (PMID 34497517, 2021). "Studies have shown that the levels of IL-1β are elevated in dogs with epilepsy and in hippocampal sclerosis patients with mesial temporal lobe epilepsy." (PMID 34421582, 2021). "Above results evidence that upregulation of HIF-1α expression in VPA-resistant epilepsy leads to increased expression of IL-1β and TNF-α." (PMID 34497517, 2021). "Studies have shown that the release of IL-1β after the activation of microglia/macrophages after epilepsy increases, and the decrease in IL-1β antagonist IL-1Ra can promote neuronal cell death." (PMID 34511129, 2021). "LPS-stimulated astrocytes can be present during inflammatory response (promote IL-1β, IL-6, and TNF-α expression) and be used to mimic epilepsy-inflammation to assess the underlying molecular or cellular mechanisms." (PMID 33776905, 2021).
epilepsy (continued). "Serum IL-1β levels were correlated only with the numbers of antiepileptic drug used in children with epilepsy (p < 0.001, r = 0.3428), suggesting drug resistant epilepsy." (PMID 32151248, 2020). "In our study, serum IL-1β levels within 48 h after afebrile seizure attacks showed correlation with the numbers of antiepileptic drugs being used by children with epilepsy." (PMID 32151248, 2020). "Induction of caspase-1 and activation of IL-1β both occur in human epilepsy, and contribute to experimentally induced acute seizures." (PMID 32907600, 2020). "Recently, the NLRP3 inflammasome, a key constituent of the inflammasome complex, has been implicated in the sterile inflammatory response via the processing of caspase-1, IL-18, and IL-1β in the setting of epilepsy and some other neurological diseases." (PMID 32005256, 2020). "In the present study, we found that levels of Iba‐1, TNF‐α and IL‐1β were increased in KA‐induced epilepsy but overexpression of circHivep2 significantly reduced the elevated levels of TNF‐α and IL‐1β." (PMID 33002329, 2020). "We investigated the expression of miR‐132 in the epileptogenic rat and human hippocampus as well as the effects of miR‐132 modulation in human cultured astrocytes after stimulation with epilepsy‐associated cytokines TGF‐β1 and IL‐1β." (PMID 31408236, 2020). "In experimental models, upregulated expression of IL-1β was also detected in epileptogenic tissues from animals with epilepsy of different etiologies." (PMID 32782321, 2020). "Interleukin-1β (IL-1β), a classically proinflammatory mediator of acute pathogenesis after injury, has been identified to initiate and aggravate seizure activity in epilepsy." (PMID 32973652, 2020). "Pearson's analysis demonstrated an interesting correlation between IL-1β and caspase-1 (r = 0.7, p < 0.001) in the epilepsy group (VV genotype)." (PMID 32219137, 2020). "The levels of pro‐inflammatory cytokines, TNF‐α and IL‐1β, and cytokine release were further decreased by circHivep2+ exosomes in the hippocampus at 72 hours after KA‐induced epilepsy." (PMID 33002329, 2020). "A recent animal study demonstrated that IL-10 inhibits IL-1β production and inflammasome activation in microglia in epileptic seizures, suggesting the potential of IL-10 in the treatment of epilepsy." (PMID 32532251, 2020). "The epilepsy group which presented generalized seizures also demonstrated a positive correlation between IL-1β vs. CASP1 and IL-6 vs. CASP3." (PMID 32219137, 2020). "Neuroinflammation and especially the role of interleukin 1 beta (IL-1β) in promoting epileptogenesis and neurodegeneration has gained increasing attention in both AD and epilepsy." (PMID 33297460, 2020). "Fourth, to distinguish neuroinflammation or neurodegeneration, such as neurocognitive dysfunction, neurocognitive tests for children with epilepsy at the time of initial and follow-ups must be conducted and compared with serum levels of α-synuclein and IL-1β." (PMID 32151248, 2020). "A number of known miR-22 targets have been linked to epilepsy, including the purinergic P2X7 receptor that drives neuroinflammation through releasing IL1β." (PMID 32825833, 2020). "Post hoc analysis with Tukey's test for multiple comparisons revealed increased IL-1β levels in the epilepsy group (AA, AV, and VV genotypes) when compared to their genotypes from the control group, respectively." (PMID 32219137, 2020). "Serum IL-1β levels showed significant correlation only with drug resistance in children with epilepsy." (PMID 32151248, 2020). "The putative role of other cytokines, such as TNF-α, IL-1β, and IL-1 receptor antagonist (IL-1RA), in the immunological activation of different stages of seizure disorders was also studied." (PMID 32532251, 2020). "The most studied cytokines regarding astrogliosis and epilepsy are interleukin-1 beta (IL-1β), IL-6, and tumor necrosis factor-alpha (TNF-α); pro-inflammatory cytokines that can be released by reactive astrocytes and activated microglia." (PMID 33324329, 2020).
epilepsy (continued). "Statistically noticeable (p = 0.0630) was that approximately 10% of dog with epilepsy (R2 = 0.105) had increased seizure frequency and IL-1β elevation." (PMID 31208341, 2019). "IL-1β levels were evaluated in CSF and serum of six healthy and 51 dogs with epilepsy (structural and idiopathic)." (PMID 31208341, 2019). "IL-1β levels should be evaluated to prove the occurrence of an inflammatory reaction in canine epilepsy." (PMID 31208341, 2019). "Regardless, there are still controversial reports on the exact role and the mechanism of the influence of IL-1β on seizures in epilepsy." (PMID 31208341, 2019). "In the CNS diseases, involvement of IL-1β is described in neurodegeneration, depression, neuro-trauma and epilepsy." (PMID 31208341, 2019). "In our research, we found that the protein expression of pro-inflammatory factors, including TNF-α, IL-1β, IL-6, and IL-10, was higher in pilocarpine-induced epilepsy." (PMID 31231220, 2019). "Bearing that in mind, we suggest direct measurement of the IL-1β in brain parenchyma of epileptic dogs, to better understand its role in seizures and epilepsy." (PMID 31208341, 2019). "In the current study IL-1β was measured in serum and CSF of dogs with epilepsy, which is to the authors’ knowledge the first canine-based study." (PMID 31208341, 2019). "Nevertheless, it was statistically noticeable (p = 0.0630) that approximately 10% of the dogs with epilepsy (R2 = 0.105) had increased seizure frequency and IL-1β elevation." (PMID 31208341, 2019). "It was reported that the levels of inflammatory cytokines including tumor necrosis factor alpha, interleukin-6, and interleukin-1 beta as well as interleukin-1 receptor antagonist significantly increased in patients with epilepsy." (PMID 32341973, 2019). "Collectively, TRPV1 promoted astrocyte migration thus helped the infiltration of pro-inflammatory cytokines (TNF, IL-1β, IL-6, and iNOS) from astrocytes into the vicinity of neurons to promote epilepsy." (PMID 31722723, 2019). "As far as the inflammatory cascade in epileptic patients is concerned, studies on individuals with focal drug-resistant epilepsy have shown a pro-inflammatory pattern with an altered interleukin-1beta/interleukin-1 receptor antagonist (IL-1β/IL-1Ra) ratio." (PMID 31156384, 2019). "With premise that it mirrors the inflammation in epilepsy, we have evaluated levels of IL-1β in CSF and serum of dogs with idiopathic and structural epilepsy." (PMID 31208341, 2019). "For example, it has been demonstrated that IL-1β, its receptor (IL-1R) and the antagonist of its receptor (IL-1Ra) are up-regulated in rodent epilepsy model after electrically and chemically induced seizures." (PMID 31156384, 2019). "The potential involvement of IL-1β in inflammatory reactions in epilepsy has attracted considerable attention and despite equivocal reports on its implication in seizures, it presents a possibility for characterizing new treatment options." (PMID 31208341, 2019). "Neuroinflammatory processes have been repeatedly shown to be activated in both experimental and human epilepsy, including the release of cytokines such as Il-1β and TNF-α." (PMID 30237424, 2018). "MMP3 can be induced by the pro-inflammatory cytokine IL-1β and is regulated by miR-155, suggesting a possible strategy to prevent epilepsy via reduction of inflammation." (PMID 30031401, 2018). "This study shows that the IL-1β monoclonal antibody combined with AMT and SPIONs can reduce the concentration of IL-1β more effectively due to improved location targeting The pathological mechanism of epilepsy is very complicated." (PMID 30514296, 2018). "Previous pediatric studies that analyzed blood and CSF of children with seizures and animal models have described a potential role of IL-1β in the genesis of seizures and later development of epilepsy." (PMID 30344507, 2018).